IFNG (interferon gamma)
Diseases named in the same sentence as IFNG in open-access papers (continued):
Sharing a sentence is not in itself a finding about the gene and the disease.
demyelinating disease (18 papers, 2007 to 2024). A broad group of disorders that affect the myelin sheaths that cover the neurons. "In other demyelinating diseases like multiple sclerosis (MS), IFNγ plays a significant role in disease pathogenesis." (PMID 38238869, 2024). "Importantly, AAT significantly impaired the IFNγ-induced inflammatory response related to the pathology and progression of neurodegenerative/demyelinating diseases." (PMID 35806409, 2022). "Thus, confirming the ability of our specific EVs to enter the CNS via the nasal delivery route and target oligodendrocytes is a significant step towards determining the utility of IFNγ-DC-EVs as a therapeutic for demyelinating disorders." (PMID 34388189, 2021). "In conclusion, we propose that Th1 cell-derived humoural factors, mainly IFNγ, induce microglial activation and the release of IL-1β that downregulates astrocytic Cx43, which might exacerbate the inflammatory processes in demyelinating disorders." (PMID 27929069, 2016). "However, it is likely that based on need (e.g., demyelinating disease) or increased neural activity (e.g., learning), increased myelin levels following IFNγ-DC-EVs treatment may be maintained." (PMID 34388189, 2021). "Increasing evidence suggests that the immune cytokine interferon-gamma (IFN-γ), secreted by activated T-lymphocytes, plays a deleterious role in immune-mediated demyelinating disorders including MS." (PMID 31997102, 2020). "Despite IFNγ being an important mediator of neuroinflammation in demyelinating disease, there are currently no studies investigating a similar role of IFNγ in neuroinflammation, demyelination, and neurodegeneration in MSA." (PMID 38238869, 2024).
iron deficiency (18 papers, 2010 to 2025). "The conversion to this dormant stage is induced by penicillin, iron deficiency, amino acid starvation, and interferon-gamma (IFN-γ)." (PMID 36155135, 2022). "Persistent in vitro infections have been induced by penicillin treatment, amino acid starvation, iron deficiency, Interferon-gamma (IFN-γ) exposure, monocyte infection, phage infection and continuous culture." (PMID 21702997, 2011).
juvenile idiopathic arthritis (18 papers, 2010 to 2025). Juvenile idiopathic arthritis (JIA) is the term used to describe a group of inflammatory articular disorders of unknown cause that begin before the age of 16 and last over 6 weeks. "Furthermore, IL-17A+IFNγ+ cells can also arise when IL-17A+ cells are stimulated with IL-12 and upon exposure to synovial fluid from juvenile idiopathic arthritis (JIA) patients." (PMID 34082814, 2021). "This is in accord with a recent report in juvenile idiopathic arthritis demonstrating that clonally expanded IL21 and IFNG co-expressing Tph promote CD11c+ double negative B cell differentiation." (PMID 38862501, 2024).
pneumonitis (18 papers, 2009 to 2025). An inflammatory process affecting the lung parenchyma. "Serial Interferon-gamma (IFN-γ) release assessed by enzyme-linked immunosorbent assay in NSCLC treated with PD-1 or PD-L1 inhibitors showed that patients with <10 IU/ml at baseline or immediately after the first dose of ICI (2-4 weeks) had more lung-irAE (pneumonitis) risk." (PMID 35558065, 2022). "Our data demonstrated that HS diet enhanced pneumonitis and enhanced inflammatory cytokine (IFNγ and IL-1β) expression in CD4+T cells in sites distal to tumor such as lung and also peripheral circulation." (PMID 35741331, 2022). "Importantly, we observed enrichment of IFNγ+ CD8+ T cells, but we also observed enrichment of Th17/Th1 cells, suggesting that there are shared and distinct mechanisms underlying ICI-induced pneumonitis depending on the tumor type." (PMID 33552049, 2020). "Many of the genes identified in the present study, such as IL2RG, NdRG, IFNG, and CXCL6, were also regulated in the mouse pneumonic plague models." (PMID 27003632, 2016). "Evaluation of T cell functionality revealed enhancement in the number of IFNγ- and IL-17-producing CD4+ T cells in the ICI group, compared with the control group, suggesting a unique contribution of these cells to the development and progression of ICI-pneumonitis." (PMID 39247203, 2024).
psoriatic arthritis (18 papers, 2013 to 2025). Joint inflammation associated with psoriasis. "In assessing the impact of probiotics on patients with psoriatic arthritis over 12 weeks, levels of the cytokine IFNγ were measured in both the treatment and placebo groups." (PMID 41211170, 2025). "We have shown that IL-10-producing Bregs in psoriatic arthritis(PsA) were decreased and inversely correlated with IFNγ+T cells (TH1 cells) and IL-17+ T cells (TH17 cells)." (PMID 32185301, 2018).
adenoma (17 papers, 2010 to 2025). A neoplasm arising from the epithelium. "Therapeutic antibody-mediated blockade of IL-25-signalling decreased intratumoral ILC2s, MDSCs and adenoma/adenocarcinoma, while increasing anti-tumor adaptive T cell and IFNγ-mediated immunity." (PMID 35658010, 2022). "The results of HE staining on lung sections show that urethane treatment induced adenomas (AD) formation in both WT and IFNγ-/- mice." (PMID 33456564, 2021). "Even if the results of the adenoma study should be handled with prudence considering the number of patients, IFNγ and IL-6 pathways partially regulate Th1 and Th2 cell network homeostasis (IFNγ in men and IL-6 in women, resp)." (PMID 22235223, 2011). "In the adenoma group, on the other hand, IFNγ and IL-6 pathways still partially regulated gender specific Th1 and Th2 cell network homeostasis but in neither sex was a significant relationship observed between IL-10 and other Th1/Th2 network components." (PMID 22235223, 2011). "In fact in healthy subjects, the sIL-2R in men and sIL-6R in women were principally related to IFNγ, which plays an important role in the development of Th1 cells; in adenoma the TNFα in men and IL-4 in women were, respectively, related to IFNγ and IL-6." (PMID 22235223, 2011). "Gender-specific IFNγ (men) and IL-6 (women) pathways still partially regulate Th1 and Th2 cell network homeostasis in adenoma patients, in contrast to colorectal patients." (PMID 22235223, 2011). "Further confirmation also came from the finding that in adenoma patients, gender-specific pathways IFNγ and IL-6 still partially regulate immune response homeostasis in men and women and in neither sex was a significant relationship observed between IL-10 and the other Th1/Th2 network components." (PMID 22235223, 2011). "In the APCmin/+ IFNγ−/− murine model, it was shown that the absence of IFN-γ induced higher number of adenomas and consequently approximately 50% of mice developed adenocarcinomas." (PMID 34681866, 2021). "Interestingly, interferon-gamma has revealed a strong inhibition effect on adenomas of ApcMin/+ATG5+/−mice without obvious side effects." (PMID 30374741, 2018).
adenovirus infection (17 papers, 2009 to 2025). "Although we have not identified which cells produce IFNγ in the β-glucan model, it has been demonstrated by our group and others that following BCG vaccination, CD4+ T cells are the major source of IFNγ, whereas after pulmonary adenovirus infection, CD8+ T cells predominantly produce IFNγ." (PMID 40624927, 2025). "In contrast, the IFNγ concentrations increased after lytic adenovirus infection, independently of whether the virus was an OAV (XVir-N-31, XVir-N-31-anti-PD-L1) or not (Ad-WT), or whether DAMPs had been released." (PMID 36077380, 2022).
aneurysm (17 papers, 2007 to 2025). Bulging or ballooning in an area of an artery secondary to arterial wall weakening. "Accumulating evidence from murine models has established that genetic ablation of CD4+ T cells confers protection against aneurysm development, mechanistically linked to attenuated interferon‐gamma (IFN‐γ) signalling pathways." (PMID 41208012, 2025). "Similarly, the hypoxia-inducible transcription factor (HIF) is associated with macrophage activity and interferon gamma levels and were previously found to be enriched in ruptured aneurysm tissue; HIF modulators therefore make sense as a drug candidate as well based on its function." (PMID 31329646, 2019). "TNFα and IFNγ-driven inflammatory processes are prominent in the pathogenesis of aneurysms due its role in activation and recruitment of immune cells to inflammatory sites, alongside secretion of pro-inflammatory cytokines and MMPs, and inducing VSMC death." (PMID 37799778, 2023). "However, similarly to IFNγ, divergent roles for TGFβ have been proposed, with increased TGFβ activity shown to associate with AAA formation, and subsequent functional blocking of TGFβ reduced aneurysm formation." (PMID 37799778, 2023). "A similar pattern was seen for IFNγ and IL10, indicating that solTNF inhibition reduced the inflammatory response in the aneurysm wall." (PMID 36186984, 2022). "Confirming this protective role for Th1 cytokines, it was recently shown that absence of both IFNγ or its downstream chemokine CXCL10 also ameliorate aneurysm development." (PMID 19582157, 2009).
gout (17 papers, 2015 to 2025). A condition characterized by painful swelling of the joints, which is caused by deposition of urate crystals. "Nonetheless, we found higher plasma levels of IL-1β, IL-1ra, IL-4, IL-6, IL-8, IL-9, IL-13, IL-17, FGF-basic, IFNγ, and TNFα in acute gouty arthritis patients." (PMID 31739430, 2019). "Here, we show that caspase-11−/− mice and their derived macrophages produce significantly reduced levels of gout-specific cytokines including IL-1β, TNFα, IL-6, and KC, while others like IFNγ and IL-12p70 are not altered." (PMID 31803174, 2019).
kidney damage (17 papers, 2011 to 2025). "Having shown that PD-L1 deficiency resulted in an increased IFNγ response and more severe kidney damage during NTN, we asked whether elevated IFNγ levels drive disease pathogenesis of nephritic PD-L1−/− mice." (PMID 30765734, 2019). "Following kidney damage, inflammatory mediators such as Interferon-gamma (IFN-γ), TNF-α, and TGF-β promote lymphangiogenesis via several mechanisms." (PMID 39578812, 2024). "IFN Gamma (IFNG): Elevated levels of proinflammatory cytokine, IFNG, are observed in nephropathic patients and involved in nephropathy complication of T2D." (PMID 34576149, 2021).
neutropenia (17 papers, 2010 to 2026). A decrease in the number of neutrophils found in the blood. "After multivariate adjustment for GVHD, CMV serostatus and neutropenia, only the association between the TLR4 1063A>G and IFNG 874T>A combination and IA remained statistically significant (p = 0.044)." (PMID 21483748, 2011). "To investigate the long-term impact of transient or sustained neutropenia on the development of L. mexicana-specific immune response, we analyzed IFNγ production in dLN cells of Genista and PMN-depleted mice as this cytokine induces macrophage-killing of Leishmania parasites." (PMID 26020515, 2015).
relapsing-remitting MS (17 papers, 2013 to 2025). "IFN-β therapy is effective in both TH1-driven and TH17-driven autoimmunity diseases such as EAE and relapsing remitting multiple sclerosis (RRMS) as IFN-β blocks TH1 associated pathologies via the inhibition of inflammatory interferon-gamma (IFN-γ) and interleukin-12 (IL-12)." (PMID 36911685, 2023). "Moreover, IFNβ, IFNγ, and TNFα play a protective role in MS, so IFNβ is the first-line treatment for relapsing-remitting MS (RRMS)." (PMID 36430309, 2022). "The increase of pro-inflammatory cytokines interferon gamma (IFN-γ), tumor necrosis factor alpha (TNF-α) and interleukin 6 (IL-6) prior to and during clinical relapse have been widely demonstrated in the literature in relapsing-remitting MS (RRMS) compared to controls." (PMID 34589733, 2021).
renal carcinoma (17 papers, 1994 to 2025). A carcinoma arising from the epithelium of the renal parenchyma or the renal pelvis. "Nine intersecting genes were screened and used to construct a prognostic model, whereby seven key biomarkers—MXD3, PLCB2, CCDC88B, DEF6, IFNG, TBC1D10C, and PLEKHN1—were significantly influenced the prognosis of renal cancer." (PMID 41357186, 2025). "Overall, in the treatment of renal cancers in vitro, checkpoint inhibition plus CIK cells resulted in an increasing cytotoxicity and a further upregulation of interferon-gamma in the presence of A-498." (PMID 32349280, 2020). "In the present study, we investigated the effect of interferon-gamma (IFN-gamma) on cellular calcium ion concentration [Ca2+]i and inositol 1,4,5-trisphosphate (Ins 1,4,5-P3) formation in the human renal carcinoma cell line CaKi-1." (PMID 7905278, 1994). "The frequencies of four effector T cell subsets, namely CD4+IFNγ+, CD8+IFNγ+, CD4+IL17+, CD8+IL17+ T lymphocytes, and two Treg subsets, CD4+CD25hiCD127lo and CD8+CD28-CD127loCD39hi Treg, were comparatively analyzed in the peripheral blood of bladder and renal cancer patients." (PMID 26824503, 2016).
viral myocarditis (17 papers, 2014 to 2025). Myocarditis that is caused by an infection with a viral agent. "The up-regulated genes were mainly enriched in the plasma membrane, interferon-gamma-mediated signaling pathway, type I interferon signaling pathway, calcium ion binding, response to the virus, viral myocarditis, cell adhesion molecules (CAMs), and Antigen processing and presentation." (PMID 36670748, 2023). "The downregulated DEGs were enriched in pathways such as those of influenza A, viral myocarditis, and TNF signaling and GO terms such as cytoplasm, cell surface, and interferon gamma-mediated signaling pathway." (PMID 29686831, 2018).
cardiac hypertrophy (16 papers, 2015 to 2024). "Knockout of Ifng exaggerated cardiac hypertrophy in systolic and diastolic heart failure, indicating a protective role of the IFNγ-mediated type II IFN signaling in cardiac pathogenesis." (PMID 37360690, 2023). "Previous studies have demonstrated the important roles of interferon-gamma (IFN-γ), tumor necrosis factor-α (TNF-α), interleukin-1beta (IL-1β), and IL6 in cardiac hypertrophy and dysfunction." (PMID 37554327, 2023).
hookworm infection (16 papers, 2005 to 2024). "In contrast, hookworm infection did interfere with antigen-specific IFNγ and IL-17 production by splenic T cells, correlating with strongly enhanced production of IL-4 by splenocytes (but not draining lymph node cells)." (PMID 36753434, 2023). "Two other studies conclude that though TH2 responses predominate in the context of hookworm infection, detectable levels of the TH1 cytokines–interferon gamma and IL-12, were also observed in response to antigen stimulation of cell supernatants from hookworm infected individuals." (PMID 18523547, 2008).
leukopenia (16 papers, 2008 to 2026). "IFNα high group was associated with leukopenia (OR(95%CI):5.81(1.29,26.20);p=0.022) and multiple autoantibodies, while IFNγ high group with rash (OR(95%CI):2.73(1.06,7.00);p=0.037)." (PMID 41694395, 2026). "Tumor-specific IFNγ-producing T-cells persisted during CY-induced leukopenia, whereas Tregs were progressively eliminated, especially intratumorally." (PMID 27341020, 2016).
pneumococcal pneumonia (16 papers, 2010 to 2024). A febrile disease caused by STREPTOCOCCUS PNEUMONIAE. "NK cells are believed to release the prominent fraction of the IFNγ evident during Gram-positive infection and they are recruited to the lung during pneumococcal pneumoniae within 6 hours of infection." (PMID 21887255, 2011).
protozoal infections (16 papers, 2009 to 2023). "The cellular immunity results suggested that the irradiated vaccine has a broad immune response where IFNγ, or type II interferon, is a cytokine that is critical for innate and adaptive immunity against viral, some bacterial, and protozoal infections." (PMID 35765479, 2022). "IFNγ, or type II interferon, is a cytokine that is critical for innate and adaptive immunity against viral, some bacterial, and protozoal infections." (PMID 29201900, 2017). "IFNG is an essential cytokine produced by both innate and adaptive immune cells, which is highly active to fight against viral, certain bacteria and protozoal infections." (PMID 28117408, 2017). "IFNG gene encodes interferon gamma (IFN-γ), a soluble cytokine that is pivotal for the host’s innate and adaptive immunity against viral, certain bacterial and protozoal infections." (PMID 25991924, 2015). "Interferon gamma (IFN-γ) is a type II interferon and is critical for innate and adaptive immunity against viral, bacterial, and protozoal infections." (PMID 31475028, 2019).
vitamin D deficiency (16 papers, 2013 to 2025). A nutritional condition produced by a deficiency of VITAMIN D in the diet, insufficient production of vitamin D in the skin, inadequate absorption of vitamin D from the diet, or abnormal conversion of vitamin D to its bioactive metabolites. "In in vitro trophoblast experiments, vitamin D deficiency decreased the expression of hCG and increased the expression of tumor necrosis factor-alpha, interleukin-6, and interferon-gamma, thereby increasing the T-helper/T-cytotoxic cell ratio." (PMID 41367918, 2025). "Strong evidence substantiates that vitamin D deficiency during pregnancy caused an imbalance in the Th1/Th2 ratio, decreased IFNγ production, but increased IL-4 concentration." (PMID 41010514, 2025). "Vitamin D deficiency shifts this system toward a pro-inflammatory state that favors Th1 and Th17 activation and increased expression of TNF, IFNγ, and IL-17, as well as elevated expression of pro-inflammatory Il-4, IL-5 and IL-13, and gut barrier dysfunction." (PMID 32093192, 2020). "Furthermore, gestational vitamin D deficiency is considered to increase IL4 concentration and decrease the Th1/Th2 ratio and IFNG production." (PMID 37520545, 2023). "As observed previously with higher doses of OVA/Alum, vitamin D deficiency enhanced the capacity of ADLN cells to proliferate and secrete cytokines like IL-4, IL-5, IL-10 (data not shown), but not IL-6, IL-17, TNF or IFNγ (data not shown)." (PMID 23826346, 2013).
anaphylaxis (15 papers, 2013 to 2025). An acute hypersensitivity reaction that occurs from exposure to an allergen. "We observed enriched representation of 15 anaphylaxis‐associated pathways and identified 15 genes involved in IgE/FcεRI signaling that were convergently modulated by IFNγ, IL‐33, IL‐4 + IL‐13, and TGFβ." (PMID 40926620, 2025).
chronic lymphocytic leukemia (15 papers, 2016 to 2025). "Consistent with this, another study showed that interferon-gamma (IFN-γ) induced IDO1 in human chronic lymphocytic leukemia cells which depended on the JAK/STAT1 signaling." (PMID 39211042, 2024). "The first case was a 77-year-old immunosuppressed individual with B cell chronic lymphocytic leukemia who exhibited increased levels of the cytokines, interleukin (IL)1β, 6, 8, 10, interferon gamma (IFN)-γ and tumor necrosis factor (TNF)-α." (PMID 35430702, 2022). "Single-agent trabectedin induced mRNA expression of IFNG and GZMB in CD8+ T cells from patients with chronic lymphocytic leukemia treated in vitro, which aligns with our findings in NK cells." (PMID 39777457, 2025).
insulinoma (15 papers, 1995 to 2025). "By qPCR analysis, we show that mouse insulinoma MIN6 cells and mouse islets accumulate the immune proteolytic β1i, β2i and β5i, and 11S mRNAs upon exposure to IFNβ or IFNγ." (PMID 23383295, 2013).
ocular toxoplasmosis (15 papers, 2010 to 2024). Ocular toxoplasmosis is an infection in the eye caused by the parasite, Toxoplasm a gondii. "This study analyzed the synthesis of Interferon gamma (IFN-γ), Tumor Necrosis Factor alpha (TNF-α), and Interleukin 10 (IL-10) in chronically infected patients which developed the symptomatic disease as cerebral or ocular toxoplasmosis." (PMID 25352834, 2014). "This study was aimed to analyze the synthesis of Interferon gamma (IFN-γ), Tumor Necrosis Factor alpha (TNF-α), and Interleukin 10 (IL-10) in chronically infected patients which developed the symptomatic disease as cerebral or ocular toxoplasmosis." (PMID 25352834, 2014).